LRRC8E (leucine rich repeat containing 8 VRAC subunit E)
Description:
Non-essential component of the volume-regulated anion channel (VRAC, also named VSOAC channel), an anion channel required to maintain a constant cell volume in response to extracellular or intracellular osmotic changes. The VRAC channel conducts iodide better than chloride and can also conduct organic osmolytes like taurine. Mediates efflux of amino acids, such as aspartate, in response to osmotic stress. The VRAC channel also mediates transport of immunoreactive cyclic dinucleotide GMP-AMP (2'-3'-cGAMP), an immune messenger produced in response to DNA virus in the cytosol. Channel activity requires LRRC8A plus at least one other family member (LRRC8B, LRRC8C, LRRC8D or LRRC8E); channel characteristics depend on the precise subunit composition. Also plays a role in lysosome homeostasis by forming functional lysosomal VRAC channels in response to low cytoplasmic ionic strength condition: lysosomal VRAC channels are necessary for the formation of large lysosome-derived vacuoles, which store and then expel excess water to maintain cytosolic water homeostasis.
Synonyms: FLJ23420
Tractability: Antibody: UniProt places it where antibodies can reach, with high confidence; its Gene Ontology location is reachable by antibodies, with high confidence; UniProt predicts a signal peptide or a membrane-spanning region. PROTAC: ubiquitination databases record sites on it; its protein half-life has been measured.
Gene: Protein-coding gene on chromosome 19 (7,888,500 to 7,902,021, forward strand). Ensembl gene ENSG00000171017.
Subcellular location: Cell membrane; Endoplasmic reticulum membrane; Lysosome membrane
Pathways (Reactome):
Transport of small molecules: Miscellaneous transport and binding events
Gene Ontology:
Molecular function: protein binding; volume-sensitive anion channel activity
Biological process: aspartate transmembrane transport; cell volume homeostasis; cellular response to osmotic stress; cyclic-GMP-AMP transmembrane import across plasma membrane; monoatomic anion transmembrane transport
Cellular component: cytoplasm; endoplasmic reticulum membrane; lysosomal membrane; monoatomic ion channel complex; plasma membrane
Genetic constraint (gnomAD): Loss-of-function variants: 9 observed, 6.59 expected, observed/expected ratio (o/e) 1.37, 90% interval 0.8 to 1.91. That is too few expected variants to judge how well the gene tolerates losing a copy. Missense variants: 1,028 observed, 1,060.1 expected, observed/expected ratio (o/e) 0.97, 90% interval 0.92 to 1.02. Synonymous variants: 485 observed, 485.49 expected, observed/expected ratio (o/e) 1, 90% interval 0.93 to 1.08.
Homologues: Orthologues: chimpanzee LRRC8E (99% identical), macaque LRRC8E (98% identical), pig LRRC8E (92% identical), dog LRRC8E (92% identical), rabbit LRRC8E (92% identical), rat Lrrc8e (91% identical), mouse Lrrc8e (90% identical), guinea pig LRRC8E (80% identical), tropical clawed frog lrrc8e (67% identical), zebrafish lrrc8da (48% identical), zebrafish si:ch211-106h11.1 (41% identical). Paralogues in human: LRRC8C (62% identical), LRRC8A (54% identical), LRRC8D (50% identical), LRRC8B (47% identical), PHLPP2 (15% identical), PHLPP1 (15% identical), SCRIB (15% identical), LRRC1 (14% identical), LRRIQ4 (14% identical), LRRC40 (14% identical), ERBIN (13% identical), LRRC7 (13% identical), and 19 more.
Diseases named in the same sentence as LRRC8E in open-access papers:
LRRC8E is named in the same sentence as 7 diseases in open-access papers, as found by Europe PMC text mining. Sharing a sentence is not in itself a finding about the gene and the disease. The quoted sentences say what the papers report.
cervical cancer (1 paper, 2025). A primary or metastatic malignant neoplasm involving the cervix. "In colorectal cancer, its downregulation promotes apoptosis and inhibits malignancy via targeting miR‐3619‐5p, while in cervical cancer, it facilitates metastasis and proliferation via the miR‐625‐5p/LRRC8E axis." (PMID 41090505, 2025).
pancreatic cancer (1 paper, 2023). "In the current study, a total of 17 genes with prognostic values have been identified, of which 8 genes (SFXN5, LRRC8E, KCNJ10, UPB1, SLC43A2, SLC38A10, ACCS, and SLC38A5) were identified for the first time in pancreatic cancer." (PMID 37333498, 2023).
tumor (3 papers, 2017 to 2024). "Other genes such as LRRC8E, HNMT, and RFC2 were downregulated in the tumor buds but upregulated in the microenvironment." (PMID 28687755, 2017).
infection (1 paper, 2025). The state of being infected such as from the introduction of a foreign agent such as serum, vaccine, antigenic substance or organism. "Disruption of Lrrc8e in recipient mice worsened infection by HSV-1 virus, which is associated with markedly increased cellular cGAMP levels." (PMID 41419196, 2025).
LRRC8E also shares sentences with these, for which no sentence is quoted: brain injury (1 paper); colorectal cancer (1); lung carcinoma (1).